SLC25A24 (solute carrier family 25 member 24)
Description:
Electroneutral antiporter that mediates the transport of adenyl nucleotides through the inner mitochondrial membrane. Originally identified as an ATP-magnesium/inorganic phosphate antiporter, it also acts as a broad specificity adenyl nucleotide antiporter. By regulating the mitochondrial matrix adenyl nucleotide pool, could adapt to changing cellular energetic demands and indirectly regulate adenyl nucleotide-dependent metabolic pathways. In vitro, a low activity is also observed with guanyl and pyrimidine nucleotides. May play a role in protecting cells against oxidative stress-induced cell death, by buffering calcium levels in the mitochondrial matrix through the formation of calcium-phosphate precipitates.
Synonyms: SCaMC-1; APC1; SCAMC1; DKFZp586G0123
Tractability: Antibody: UniProt predicts a signal peptide or a membrane-spanning region. PROTAC: ubiquitination databases record sites on it; its protein half-life has been measured.
Gene: Protein-coding gene on chromosome 1 (108,134,043 to 108,200,849, reverse strand). Ensembl gene ENSG00000085491.
Subcellular location: Mitochondrion inner membrane
Subcellular location (Human Protein Atlas): Mitochondria
Gene Ontology:
Molecular function: adenine nucleotide transmembrane transporter activity; ADP:phosphate antiporter activity; ATP transmembrane transporter activity; ATP:phosphate antiporter activity; calcium ion binding
Biological process: adenine nucleotide transport; cellular response to calcium ion; cellular response to oxidative stress; mitochondrial ATP transmembrane transport; mitochondrial transport; ADP transport; transmembrane transport
Cellular component: membrane; mitochondrion; mitochondrial inner membrane
Genetic constraint (gnomAD): Loss-of-function variants: 34 observed, 40.92 expected, observed/expected ratio (o/e) 0.83, 90% interval 0.63 to 1.11. The upper end of that interval is the gene's LOEUF score, 1.11, which puts it in group 4 of 6, group 1 being the genes least tolerant of losing a copy. Missense variants: 415 observed, 455.07 expected, observed/expected ratio (o/e) 0.91, 90% interval 0.84 to 0.99. Synonymous variants: 158 observed, 168.37 expected, observed/expected ratio (o/e) 0.94, 90% interval 0.82 to 1.07.
Gene-disease validity (ClinGen):
ClinGen rates the evidence that SLC25A24 causes each of these diseases.
Fontaine progeroid syndrome (autosomal dominant): Definitive.
Homologues: Orthologues: chimpanzee SLC25A24 (99% identical), macaque SLC25A24 (99% identical), pig SLC25A24 (96% identical), mouse Slc25a24 (93% identical), rat Slc25a24 (92% identical), dog SLC25A24 (86% identical), guinea pig SLC25A24 (86% identical), rabbit SLC25A24 (85% identical), tropical clawed frog slc25a24 (72% identical). Paralogues in human: SLC25A25 (61% identical), SLC25A23 (59% identical), SLC25A41 (37% identical), SLC25A12 (24% identical), SLC25A13 (23% identical), SLC25A16 (17% identical), SLC25A3 (17% identical), SLC25A19 (17% identical), SLC25A29 (17% identical), SLC25A42 (17% identical), SLC25A37 (16% identical), SLC25A4 (16% identical), and 37 more.
Diseases named in the same sentence as SLC25A24 in open-access papers:
SLC25A24 is named in the same sentence as 47 diseases in open-access papers, as found by Europe PMC text mining. Sharing a sentence is not in itself a finding about the gene and the disease. The quoted sentences say what the papers report.
Fontaine progeroid syndrome (5 papers, 2019 to 2025). "They found a mutation in the SLC25A24 gene, which is linked to Fontaine progeroid syndrome, a rare genetic disorder causing early aging symptoms." (PMID 41271664, 2025). "Two recurrent missense mutations in SLC25A24 have been reported in Gorlin-Chaudhry-Moss syndrome (GCMS) and Fontaine syndrome, which are progeroid syndromes associated with accelerated aging." (PMID 36277487, 2022). "Given that both syndromes are caused by an autosomal dominant mutation in SLC25A24, either de novo p.Arg217Cys or p.Arg217His mutation, the two syndromes are now designated with a common name: Fontaine progeroid syndrome." (PMID 32340404, 2020). "Fontaine progeroid syndrome (FPS) is an autosomal dominant condition resulting from an abnormality in SLC25A24, with only 12 reported cases so far1,2." (PMID 41271664, 2025). "The connection between the mutations in SLC25A24 and the symptoms of Fontaine progeroid syndrome is not clear." (PMID 32340404, 2020). "Because a de novo missense mutation of the solute carrier family 25 member 24 (SLC25A24) gene was suggested to be the common genetic basis of both syndromes, it has been proposed recently that they be integrated into a single disorder under the name of Fontaine progeroid syndrome (FPS)." (PMID 31775791, 2019).
breast carcinoma (3 papers, 2020 to 2022). "It was found that the mutation rate of SLC25A25 was the highest in breast cancer cell lines and SLC25A24 had a higher mutation level in colorectal cancer cell lines." (PMID 36254139, 2022). "LongGF also detected more potential novel gene fusions (ACTB:H3F3B, SLC25A24:NBPF6, STMN1:ACTG1), and these genes were reported to be associated with breast cancer." (PMID 33372596, 2020). "Slc25a24, Cnpy2 and BAX overexpression was reported in breast cancer." (PMID 36151122, 2022).
colon adenocarcinoma (3 papers, 2021 to 2022). "Among surgical resection specimens of colon adenocarcinoma and paired colonic epithelium, 72 and 78 of 79 cases with progressive disease were successfully stained and evaluated for SLC25A5 and SLC25A24, while 87 and 103 of 106 cases with advanced disease finished the same work." (PMID 35288533, 2022).
colon cancer (3 papers, 2022). "SLC25A24 mutation could alter its expression in skin melanoma, hepatocellular carcinoma, and colon cancer." (PMID 36254139, 2022). "Low expression of SLC25A5 (p < 0.01) and SLC25A24 (p < 0.001) was observed in colon cancer compared to that in paired colonic epithelium." (PMID 35288533, 2022). "Although SLC25A5 and SLC25A24 displayed elevated expression compared to samples from The Genotype-Tissue Expression (GTEx), both were relatively lowly expressed in colon cancer based on samples from TCGA-COAD, which requires further experimental validation." (PMID 35288533, 2022). "Regarding the diagnostic efficacy of colon cancer, the AUCs of ROCs were 0.773 (CI: 0.736–0.809) for SLC25A5 and 0.771 for SLC25A24 (CI: 0.734–0.807)." (PMID 35288533, 2022). "To further evaluate the clinical value of SLC25A5 and SLC25A24 in colon cancer, we performed a series of bioinformatic investigations." (PMID 35288533, 2022). "To explore the function of SLC25A5 and SLC25A24 in colon cancer, we executed several cytological experiments in vitro." (PMID 35288533, 2022). "For example, in colon cancer, tumor derived CCL5 can recruit fibroblasts through the CCR5/SLC25A24 signaling pathway to promote angiogenesis and collagen formation, thereby affecting the tumor microenvironment." (PMID 36033472, 2022). "Although high expression of most DEMs indicated a longer survival time of patients with colon cancer, only that of SLC25A5 (HR = 0.58, log-rank p < 0.01, 95% CI 0.38–0.90) and SLC25A24 (HR = 0.58, log-rank p < 0.01, 95% CI 0.39–0.85) met statistical significance." (PMID 35288533, 2022). "Although it may seem paradoxical, our results suggested that SLC25, and in particular, SLC25A5 and SLC25A24, might be involved in the EGFR and ERK-MAPK signaling pathways in colon cancer and potentially serve as treatment targets." (PMID 35288533, 2022).
Obesity (3 papers, 2021 to 2024). Accumulation of substantial excess body fat. "Slc25a24 knockout mice are resistant to high-fat diet-induced obesity, as indicated by reduced liver weight and triglyceride deposition in the liver, and a prospective observational study of the population revealed that SLC25A24 is also a new candidate gene for susceptibility to obesity in humans." (PMID 39850557, 2024). "However, there are reports on six of Slc genes (Slc2a10, Slc5A1, Slc5a9, Slc6A14, Slc16A5, Slc25A24) in metabolic diseases including obesity, dyslipidemia, NAFLD, and T2DM." (PMID 34659115, 2021). "This study suggests that Slc25a24 may be required for adipose tissue expansion and a novel candidate gene in the control of obesity." (PMID 34659115, 2021). "It is also important to note that the novel EC proteins, APP, CAD, BRD2 (which is part of DKFZp313H139), CST3, GRN, PPM1G and ZC3H4, have all been reported to be positively associated with obesity or adiposity, whilst the novel EC protein SLC25A24 may even prevent obesity and promote leanness." (PMID 37760635, 2023). "Slc25a24 seems to have the same activity in the knockout mice, which were protected from HFD-induced obesity and hepatic steatosis." (PMID 34659115, 2021).
conduct disorder (2 papers, 2021 to 2024). A disorder diagnosed in childhood or adolescence age group characterized by aggressive behavior, deceitfulness, destruction of property or violation of rules that is persistent and repetitive, and within a one year period. "In adolescent girls with conduct disorder, elevated levels of callous–unemotional traits correlated with decreased SLC25A24 gene expression, while in typically developing girls, conduct disorder traits were positively associated with SLC25A24 gene expression]." (PMID 39020437, 2024). "Notably, ADARB1 variants are associated with suicide attempt in patients with psychiatric disorders, and SLC25A24 relates to conduct disorder." (PMID 39020437, 2024).
Insulin resistance (2 papers, 2022 to 2025). Increased resistance towards insulin, that is, diminished effectiveness of insulin in reducing blood glucose levels. "These genes have been involved in insulin resistance and secretion (ATM, PTPRN2, PSMD10, and NSF), adipogenesis (SLC25A24 and PAX8), inflammatory processes (TNFRSF8 and SLIT3), and mitochondrial processes (PM20D1 and LCLAT1)." (PMID 36535927, 2022).
adenoma (1 paper, 2021). A neoplasm arising from the epithelium. "The expression of HIGD1A exhibited a significant reduction in two subtypes of adenoma and six subtypes of CRC, while the down-regulation of SUCLG2 and SLC25A24 showed more advantages in rectal mucinous adenocarcinoma." (PMID 34174878, 2021).
autism (1 paper, 2012). Persistent deficits in social interaction and communication and interaction as well as a markedly restricted repertoire of activity and interest as well as repetitive patterns of behavior. "The expression of DNAJC19, DNM1L, LRPPRC, SLC25A12, SLC25A14, SLC25A24 and TOMM20 were consistently reduced in at least two of the brain regions of autism patients compared to controls." (PMID 23116158, 2012). "The expression of DNAJC19, DNM1L, LRPPRC, SLC25A12, SLC25A14, SLC25A24 and TOMM20 were reduced in at least two of the brain regions of autism patients." (PMID 23116158, 2012). "The expression of SLC25A24 was reduced in the MC and THL of autism patients." (PMID 23116158, 2012).
breast invasive cancer (1 paper, 2022). "SLC25A24 mutation showed the highest HR in breast invasive cancer among all SLC25 genes, and it also showed certain risk effects in mesothelioma, ovarian serous cystadenocarcinoma, and thyroid carcinoma." (PMID 36254139, 2022).
cholangiocarcinoma (1 paper, 2022). A carcinoma that arises from the intrahepatic biliary tree (intrahepatic cholangiocarcinoma) or from the junction, or adjacent to the junction, of the right and left hepatic ducts (hilar cholangiocarcinoma). "SLC25A4 and SLC25A24 had more copy number deletion in cholangiocarcinoma, sarcoma, and lung squamous cell carcinoma." (PMID 36254139, 2022).
colorectal tumors (1 paper, 2021). "Next, to further understand the potentials of HIGD1A, SUCLG2, and SLC25A24 as the IPFs for CRC, we investigated their mRNA expression in unique datasets of CRC and different subtypes of colorectal tumors through the Oncomine database." (PMID 34174878, 2021).
glioma (1 paper, 2024). A benign or malignant brain and spinal cord tumor that arises from glial cells (astrocytes, oligodendrocytes, ependymal cells). "Summarizing the MR results presented in the heatmap, we observed that SRA1, SCDF1, SLC25A24, ZSCAN23, and ZSCAN26 were notably associated with glioma risk across at least two cell types, with consistent MR estimates, indicating potential cross‐cell effects of these genes." (PMID 39722126, 2024).
hepatocellular carcinoma (1 paper, 2022). A malignant tumor that arises from hepatocytes. "SLC25A24 was upregulated in hepatocellular carcinoma while SLC25A25 was downregulated." (PMID 36254139, 2022).
Lipoatrophy (1 paper, 2022). Localized loss of fat tissue. "As an example, MFN2 encoding mitofusin 2 has been involved in the lipodystrophic Launois-Bensaude syndrome, and SLC25A24 encoding a calcium-binding mitochondrial carrier protein has been involved in a complex progeroid syndrome with lipoatrophy." (PMID 35341481, 2022).
ovarian carcinoma (1 paper, 2022). A malignant neoplasm originating from the surface ovarian epithelium. "Relatively high mutation rates were also observed in ovarian cancer cell lines for SLC25A13, SLC25A24, SLC25A41, and SLC25A23 and in skin cancer cell lines for SLC25A13, SLC25A8, and SLC25A12." (PMID 36254139, 2022).
ovarian serous cystadenocarcinoma (1 paper, 2022). A malignant serous cystic epithelial neoplasm arising from the ovary. "Besides, the mutation of many SLC25s made high-risk effects on the prognosis of ovarian serous cystadenocarcinoma such as SLC25A8, SLC25A24, SLC25A25, and SLC25A31." (PMID 36254139, 2022).
rectal mucinous adenocarcinoma (1 paper, 2021). "This suggested that SUCLG2 and SLC25A24 might be used as helper genes for HIGD1A in clinical diagnosis, which might improve the diagnostic accuracy of rectal mucinous adenocarcinoma." (PMID 34174878, 2021).
skin melanoma (1 paper, 2022). "In skin melanoma, the mutation of SLC25A24 and SCL25A27 could affect their expression." (PMID 36254139, 2022).
uterine corpus endometrial carcinoma (1 paper, 2022). A endometrial carcinoma (disease) that involves the body of uterus. "Almost all SLC25s had high mutation frequency in uterine corpus endometrial carcinoma, including SLC25A12, SLC25A13, SLC25A14, SLC25A23, SLC25A24, and SLC25A25." (PMID 36254139, 2022).
Wiedemann-Rautenstrauch syndrome (1 paper, 2025). Wiedemann-Rautenstrauch syndrome is a very rare disorder with features of premature aging recognizable at birth, decreased subcutaneous fat, hypotrichosis, relative macrocephaly and dysmorphism. "Wiedemann-Rautenstrauch Syndrome is a heterogeneous disorder caused by a pathogenic variant found in one of a few genes, including POLR3A, FBN1, CAV1, and SLC25A24." (PMID 40440483, 2025).
tumor (12 papers, 2013 to 2024). "A previous study of patients with EBV-associated Burkett's lymphoma found that patient death was associated with SLC25A24 down-regulation when the tumor was EBV-positive." (PMID 34799401, 2021). "In this study, we found that SLC25A24 was highly expressed in fibroblasts surrounding the tumor buds at the invasive front." (PMID 35241150, 2022). "Representative pictures showed that SLC25A5 and SLC25A24 were differentially expressed in tumor and adjacent normal tissues." (PMID 35288533, 2022). "The results revealed that SLC25A24 was highly expressed in the fibroblasts surrounding the tumor buds at the invasive front." (PMID 35241150, 2022). "CCL5 derived from tumor buds also positively regulated the expression of solute carrier family 25 member 24 (SLC25A24) in fibroblasts, which may have activated the p Akt/pmTOR signal transduction pathway." (PMID 37141250, 2023). "Tumor bud-derived CCL5 could also positively regulate solute carrier family 25 member 24 (SLC25A24) expression in fibroblasts, potentially activating pAkt-pmTOR signaling." (PMID 35241150, 2022). "CCL5 also recruits fibroblasts via the SLC25A24-pAkt-pmTOR signaling pathway in fibroblasts, which further promotes angiogenesis and collagen synthesis through recruited fibroblasts, ultimately creating a pro-tumor microenvironment." (PMID 36387070, 2022). "Furthermore, the PFS analyses revealed that the decreased expression of HIGD1A and SLC25A24 accelerated the tumor malignancy." (PMID 34174878, 2021). "In vivo, in tumor xenografts of shCCL5-transfected CRC cells, reduced SLC25A24 expression was observed in fibroblasts." (PMID 35241150, 2022). "As shown, of the various tumor pathological grades, the expression levels of SLC25A4 (P < 0.01), SLC25A11 (P < 0.0001), SLC25A24 (P < 0.01), SLC25A37 (P < 0.01), SLC25A42 (P < 0.01), SLC25A43 (P < 0.0001), SLC25A44 (P < 0.05) and SLC25A45 (P < 0.05) were significantly different." (PMID 36514121, 2022). "Consequently, HIGD1A, SUCLG2, and SLC25A24 were all down-regulated in CRC and exhibited a stably declined expression throughout the tumor progression." (PMID 34174878, 2021).
cancer (3 papers, 2013 to 2022). A tumor composed of atypical neoplastic, often pleomorphic cells that invade other tissues. "SLC25A24 was highly expressed in the 10 common cancer types." (PMID 36254139, 2022). "In addition, gene sets enriched in cancer-related phenotypes and signaling pathways for SLC25A5 and SLC25A24 were also investigated." (PMID 35288533, 2022).
SLC25A24 also shares sentences with these, for which no sentence is quoted: colorectal cancer (3 papers); progeroid syndrome (3); cecum adenocarcinoma (1); colon mucinous adenocarcinoma (1); copy number variation (1); dyslipidemia (1); Hepatic steatosis (1); lipodystrophy (1); lung squamous cell carcinoma (1); mesothelioma (1); metabolic disease (1); mitochondrial disease (1); Neonatal onset (1); osteosarcoma (1); prostate adenocarcinoma (1); prostate carcinoma (1); psychiatric disorder (1); rectal adenocarcinoma (1); rectosigmoid adenocarcinoma (1); renal carcinoma (1); sarcoma (1); skin cancer (1); stomach adenocarcinoma (1); thyroid carcinoma (1).